EGFR (epidermal growth factor receptor)
Diseases named in the same sentence as EGFR in open-access papers (continued):
Sharing a sentence is not in itself a finding about the gene and the disease.
breast carcinoma (continued). "Combination of EGFR-CAR NK-92 cells with herpes simplex virus 1-based oncolytic virus (oHSV-1) results in increased efficiency in killing a breast cancer cell line engrafted into the brain." (PMID 33287875, 2020). "Fluorescent single-cell analysis of SKBR3 breast cancer cells dual-labeled for EGFR and HER2 revealed a heterogeneous expression for receptors within both the cell population as well as within individual cells." (PMID 33260837, 2020). "In general, the percentage of individuals with abnormal levels of one or more of EGFR or EGFR ligands in serum were found to be nearly twice as high in the breast cancer group compared to the healthy control group (35.9% and 19.5%, respectively)." (PMID 32317675, 2020). "One of studies showed that gefitinib can increase the mitochondrial EGFR (mtEGFR) levels in breast cancer cells." (PMID 31936895, 2020). "therapeutically to target EGFR-expressing cancerous tissues with nucleic acid drugs for breast cancer." (PMID 33262977, 2020). "Triple-negative breast cancer (TNBC) is a breast cancer subtype which is heterogeneous in nature and has the characteristic of negativity for estrogen receptor (ER), progesterone receptor (PR), and epidermal growth factor receptor (EGFR or HER2)." (PMID 31936263, 2020). "In our experiments, hypoxia changed the phenotype of all investigated cell lines to an EGFR/ErbB-2 double-positive phenotype, which characterizes aggressive breast cancers." (PMID 32466213, 2020). "Such as the combination of paclitaxel targeted BCL2 and lapatinib targeted EGFR was reported to be effective for HER2 + breast cancer in the clinical trial phase 3." (PMID 32523951, 2020). "The 548 samples included 148 luminal A (ER+/PR+, HER2−, Ki-67<20%), 91 luminal B (ER+/PR+, HER2+/Ki-67≥20%), 113 HER2+ (ER-, PR-, HER2+), and 196 basal cell-like (ER−, PR−, HER2−, CK5/6+ and/or EGFR+) breast cancers." (PMID 33299650, 2020). "It has been shown that it is also dependent on the release of amphiregulins, HB-EGF and TGF-α, and the activations of EGFR/ErbB1 receptors on prostate cancer cells and EGFR/ErbB1 and ErbB2 on breast cancer cells." (PMID 32466280, 2020). "SKBR3 cells, a model for HER2 positive breast cancer, express low levels of EGFR based on RNA analysis." (PMID 33260837, 2020). "Launching from this success, several clinical trials have been completed in breast cancer patients using EGFR-targeted TKIs, either as monotherapy or in addition to chemotherapy." (PMID 32552913, 2020). "Evidence has proved that quercetin is effective in preventing cancer progression by inhibiting the EGFR signaling pathway and can reverse tamoxifen resistance in breast cancer cells." (PMID 32964029, 2020). "ER, PR, and HER2 are the hormone receptors that control the growth of breast cancer cells, accompanied by the epidermal growth factor receptor (EGFR)." (PMID 32121012, 2020). "The same authors found in an MDA-231 breast cancer cell line that SHIP2 promotes cell migration and this effect is associated with sustained EGFR-AKT signaling and increased expression of chemokine receptor CXCR421." (PMID 32179834, 2020). "Our previous study have shown that EGFR promotes breast cancer invasion through downstream p44/p42 MAPK (ERK1/2) signaling, and resistin is known to enhance angiogenesis in human osteosarcoma cells via the ERK1/2 signaling." (PMID 33313320, 2020). "Since more than half of the triple-negative (TNBC) breast cancers are related to epidermal growth factor receptor (EGFR), a therapeutic option is the use of tyrosine kinase inhibitors (TKIs)." (PMID 32882920, 2020). "Our studies are consistent with other studies that demonstrate that the phosphorylation of EGFR at T654 maintains receptor stability in vitro, and EGFR overexpression enhances breast cancer metastasis in vivo." (PMID 31597954, 2020).
breast carcinoma (continued). "The same method was used to load exosomes with miRNA to the epidermal growth factor receptor (EGFR) expressed in breast cancer cells, indicating that exosomes can be used therapeutically to target EGFR-expressing cancerous tissues with nucleic acid drugs." (PMID 33396739, 2020). "Altogether, we have shown that HUNK promotes metastasis by phosphorylating EGFR, resulting in downstream signaling events that drive metastatic behavior of breast cancer cells." (PMID 31597954, 2020). "Surprisingly, De Cola and colleagues have reported the upregulation of miR-205 in patient-derived breast cancer stem cells, with the consequent downregulation of Epidermal Growth Factor Receptor (EGFR) and HER2 and resistance to Lapatinib." (PMID 33375067, 2020). "Separate from the two prior studies, our study showed that HUNK phosphorylates the epidermal growth factor receptor (EGFR) at threonine (T) 654 to regulate breast cancer metastasis, providing a discrete HUNK-kinase dependent mechanism for this process." (PMID 32676513, 2020). "Breast cancer patients whose tumors were both resistin-positive and strongly EGFR-positive, or were both strongly resistin-positive and strongly EGFR-positive, had worse RFS than all other breast cancer patients." (PMID 33313320, 2020). "In preclinical study of breast cancer, heparin binding EGF, ligand of EGFR, can enhance the adhesion between tumor cells and brain endothelial cells, and help tumor cells penetrate the blood-brain barrier in breast cancer." (PMID 33537237, 2020). "The uptake of 89Zr-nimotuzumab and 89Zr-panitumumab was also specific and correlated well with the EGFR expression of tumors in colorectal and breast cancer models." (PMID 32560337, 2020). "Once expressed by ERRα, GREM1 activates EGFR, the ERRα upstream regulator, and ultimately augments the activity of ERRα in breast cancer cells in a positive feedback mechanism." (PMID 32572171, 2020). "An approved cancer drug, Erlotinib Hydrochloride, epidermal growth factor receptor inhibitor, has shown a very positive response rate when treated combinedly with Capecitabine and Docetaxel in advanced breast cancer patients." (PMID 32503412, 2020). "Selective binding to EGFR-positive breast cancer and other overexpressing tumor cell lines described for 425(scFv)-SNAP-AURIF and panitumumab-derived 1171(scFv)-SNAP-AURIF, was also confirmed on EGFR-positive breast cancer biopsies." (PMID 33014289, 2020). "There is also evidence that ECM1 potentiates the phosphorylation of epidermal growth factor receptor (EGFR) and extracellular signal-regulated kinase through physical interaction with EGFR and activation of EGFR signaling in breast cancer development." (PMID 32292720, 2020). "EGFR is one of the main molecules altered in cancer, and a specific antibody-based drug, Gefitinib, has been approved for its use in breast cancer." (PMID 31945087, 2020). "Yu and colleagues proved that EMT exists in human breast cancer specimens, and they used three antibodies (EGFR, HER2 and EpCAM) to capture breast cancer cells more efficiently." (PMID 32823926, 2020). "A hormone receptor-positive tumor is the breast cancer that has theses following receptors, estrogen receptor (ER), progesterone receptor (PR), and epidermal growth factor receptor (HER-2/Neu)." (PMID 32155880, 2020). "Looking forward, these findings have the potential to translate into a positive impact for the overall survival of patients with metastatic breast cancers that over-express EGFR." (PMID 31597954, 2020). "HER2, also named ErbB2, belongs to the epidermal growth factor receptor (EGFR) family, and is overexpressed in 20–30% of breast cancer cases." (PMID 32511274, 2020).
breast carcinoma (continued). "Taken together, we propose that CD99 agonist ligands have potential as novel therapeutic drug candidates to suppress human breast carcinoma via inhibition of EGF-mediated EGFR signaling." (PMID 33050232, 2020). "Tarceva and Iressa both of which are EGFR inhibitors, are used as clinical targeted therapies for breast cancer." (PMID 32410830, 2020). "The signal transduction of α6β4 pathway works together with EGFR clustering to promote tumor cell motility and invasion of breast cancer." (PMID 32850805, 2020). "As expected, EGFR protein expression is highest in the TNBC cell lines compared to those from other breast cancer subtypes." (PMID 32552913, 2020). "The JAK2 → STAT3 pathway also highly likely depends on the activation of EGFR, as similar signal transduction occurs on breast cancer cells." (PMID 32466280, 2020). "Activation of EGFR signaling via CCR1 has been shown to contribute to breast cancer invasion and metastasis." (PMID 32963283, 2020). "The activation of EGFR signaling by ANO1 also promotes the activation of Ca2+/Calmodulin-dependent kinase II (CAMKII) signaling in breast cancer cells." (PMID 32357567, 2020). "In the HER2+/EGFR+ breast cancer cell lines examined here, EGF by itself already induced high levels of AP-1 protein, but only low levels of invasion related gene expression and subsequent cell invasion." (PMID 32350443, 2020). "The EGFR and ER signaling pathways are known to interact through a complex crosstalk and this crosstalk plays an important role in breast cancer pathogenesis." (PMID 32317675, 2020). "In particular, the epidermal growth factor receptors (EGFR) showed overexpressions in prostate or breast cancers; therefore, EGFR acts as a potential candidate for targeting the gene complexes at cancer sites." (PMID 32580366, 2020). "In a similar approach, exosomes from HEK293 cells engineered to produce an EGFR-specific peptide ligand, and transfected with let-7a mimic, delivered let-7a mimic to EGFR-expressing breast cancer xenografts and inhibited their growth." (PMID 32117755, 2020). "Specifically, EGFR is more frequently overexpressed in TNBC than other subtypes of breast cancer and has been recognized as a factor for poor prognosis." (PMID 32917240, 2020). "Taken together, we conclude that bisecting N-GlcNAc on EGFR inhibits malignant phenotype of breast cancer via down-regulation of EGFR/Erk signaling." (PMID 32612952, 2020). "They utilize PD1 and EGFR targeted nanostars for the MDA‐MB‐231 breast cancer cell line employing 170 μg mL−1 functionalized nanostars and advocate that they can control cell death specifically at the laser‐irradiated zone." (PMID 32775148, 2020). "EGFR overexpression has been noted in at least 50% of TNBCs, which is higher than other breast cancer subtypes." (PMID 35582228, 2020). "HEK293 cells were transfected with the GE11 peptide, which has a high binding affinity for the epidermal growth factor receptor (EGFR) protein, which is elevated in many epithelial cancers, including breast cancer." (PMID 32102476, 2020). "In particular, EGFR (ErbB1 and HER1) are associated with a variety of solid tumor malignancies and the overexpression of ErbB2 (HER2) is also found in 20–30% of breast cancers." (PMID 33371333, 2020). "Using EGFR‐expressing breast cancer xenograft model, they showed that GE11‐positive exosomes containing let‐7 suppress tumorigenesis." (PMID 32618144, 2020). "Epidermal growth factor receptor (EGFR) signaling promotes breast cancer cell proliferation and tumorigenesis." (PMID 32375405, 2020). "Therapies that target the epidermal growth factor receptor (EGFR) have variable and unpredictable effects in breast cancer." (PMID 33614479, 2020).
breast carcinoma (continued). "EYA2 promoted breast cancer cellular proliferation and distant metastasis as the downstream of EGFR." (PMID 32550045, 2020). "In summary, these results show that ΔNp63 is necessary for the activation of the EGFR-, and AP-1-dependent invasion gene program induced by TGFβ in multiple breast cancer cell lines." (PMID 32350443, 2020). "These GE11 expressing exosomes can bind to EGFR on EGFR-positive breast cancer cells in mice, delivering their let-7 cargo as treatment strategy." (PMID 33050562, 2020). "Another important member of the ErbB receptor family, which plays a major role in breast cancer signaling, is the EGFR." (PMID 32660617, 2020). "ERβ-suppressed breast cancer cells have a less aggressive phenotype characterized by reduced expression of proteolytic enzymes, PGs and EGFR/IGF-IR and inhibited JAK/STAT signaling." (PMID 33543032, 2020). "The role of EGFR signalling, and in particular of EGFR ligands, in osteoclastogenesis is known from breast cancer co-culture models and non-small cell lung cancer (NSCLC) models, where EGFR inhibition with TKIs was shown to prevent osteoclast differentiation." (PMID 33228060, 2020). "In the present study, we demonstrated that GREM1 physically interacted with EGFR in breast cancer cells and thereby activates EGFR signalling." (PMID 32572171, 2020). "This is in line with previous studies that reported a link between expression of YB-1 and EGFR in breast cancer patients." (PMID 33003386, 2020). "Overall, the results indicate EGFR-pathway dysregulation in subgroups of early-stage breast cancer patients that can be identified by measuring levels of EGFR and EGFR ligands in the blood." (PMID 32317675, 2020). "The emerging role of treatments co-targeting the EGFR system in breast cancer has increased the need to identify companion biomarkers." (PMID 33024132, 2020). "We have previously reported that MICAL2 is involved in the regulation of breast cancer cell migration through the suppression of EGFR degradation." (PMID 33520979, 2020). "In pancreatic and breast cancer cell line models, EGFR overexpressing cancer cells are shown to contain two distinct subsets of EGFR localization, which are plasma EGFR (pmEGFR) and mitochondria EGFR (mtEGFR)." (PMID 32872164, 2020). "In our previous study, we confirmed that GREM1 promotes breast cancer proliferation through EGFR activation, so we confirmed that the increase in MMP13 expression by GREM1 is through EGFR activation." (PMID 33287358, 2020). "This is consistent with previous studies which demonstrated that miR-141 is an important modulator of the EGFR signaling pathway as it targets EGFR, preventing its translation in breast cancer cells." (PMID 33202602, 2020). "On the other hand, EGFR revealed rho=0.72 in our study, while in breast cancer a correlation between rho=0.15–0.3 was found." (PMID 33324562, 2020). "Experimental studies support the observation that over-expression of EGFR promotes metastatic phenotypes in human breast cancer cells." (PMID 31597954, 2020). "This is further compacted by our findings of a significant correlation between Annexin A2 and EGFR expression and by the observation that breast cancers found to have EGFR overexpression are more commonly ER negative than ER positive." (PMID 32629869, 2020). "Although the combination of ERK1/2 and EGFR blockade in breast cancer has been demonstrated before using MEK1/2-inhibitors, combination in the context of CAM-DR or COL1 dependency have not been described so far." (PMID 32668815, 2020). "It has been shown that EV can also efficiently deliver miRNAs to epidermal growth factor receptor (EGFR)-expressing breast cancer cells." (PMID 32942702, 2020).
breast carcinoma (continued). "In the interplay between CSCs and TAMs, a putative role for the signal transducer and activator of transcription 3 (STAT3) pathway has been demonstrated in breast cancer models via a novel paracrine EGFR/Stat3/Sox-2 axis." (PMID 32630659, 2020). "The T798M mutation in HER2 showed increased autophosphorylation activity and preference for heterodimerization with EGFR in human breast cancer cells." (PMID 33083021, 2020). "Our study suggests that CD99-derived agonist ligands inhibit EGF-induced EGFR dimerization through impairing RhoA-Rac1 signaling-mediated reorganization of the actin cytoskeleton, thereby contributing to the suppression of breast cancer growth." (PMID 33050232, 2020). "Analysis of data from a subset of breast cancer patients has shown that GPER-1 expression has also been positively correlated with overexpression of EGFR." (PMID 33117280, 2020). "On the other hand, EGFR is expressed in a wide range of breast cancer cell lines at different levels." (PMID 33050232, 2020). "This cohort included patients in which NGS testing revealed positivity for targets such as HER2/neu (ERBB2) in breast cancer specimens, androgen receptor (AR) in prostate cancer, BRAF in melanoma and EGFR mutation in NSCLC." (PMID 32760731, 2020). "For example, SMs targeting multiple IAPs promote apoptosis in response to the ERBB antagonists, trastuzumab, lapatinib, or gefitinib, in Her2-overexpressing breast cancer cells, or gefitinib in EGFR-overexpressing breast cancer cells." (PMID 32325691, 2020). "Our evidence suggests that combined high levels of resistin and EGFR expression correlate with survival in patients with breast cancer." (PMID 33313320, 2020). "Another study demonstrated multiplex profiling of oestrogen receptor (ER), progesterone receptor (PR), and epidermal growth factor receptor (EGFR) expression in breast cancer tissue and normal tissue sections, using AuNP-based SERS tags." (PMID 33276535, 2020). "In breast cancer the EGFR/ERs crosstalk is crucial in regulating MMPs expression and functional cell properties." (PMID 33050027, 2020). "EV EGFR levels were on average over eight times higher in breast cancer patients compared to healthy patients." (PMID 33143170, 2020). "In breast cancer patients, EGFR expression is strongly correlated with tumor uptake of the glucose analogue, 18F-FDG." (PMID 31936350, 2020). "Beta-sitosterol bound to EGFR/MYC, inhibiting breast cancer growth through ErbB or Estrogen pathway." (PMID 32978480, 2020). "In summary, we show that the phosphorylation of EGFR at T654 corresponds to increased metastatic potential in vitro and in vivo, and correlates with higher stage human breast cancers." (PMID 31597954, 2020). "Elevated EGFR expression is observed in 54% of basal-type breast cancers, an aggressive type of triple negative breast cancer associated with poor survival." (PMID 33260837, 2020). "The SHIP2-Cbl interaction in MDA-MB-231 breast cancer cells prevented c-Cbl ubiquitination of EGFR, thereby suppressing ligand-induced EGFR degradation." (PMID 33276499, 2020). "The findings indicate that in subgroups of breast cancer patients, the EGFR-pathway is more involved in the malignant potential than in others." (PMID 33024132, 2020). "Further, knockdown of ANO1 in breast cancer YMB-1 cells also resulted in reduced mRNA levels of HER2 EGFR, suggesting the regulation at a transcriptional level." (PMID 33250781, 2020). "Lapatinib is a multitarget TKI selective for human epidermal growth factor receptor 2 (HER2) and epidermal growth factor receptor (EGFR) used for treatment of HER2-positive breast cancer." (PMID 32751576, 2020).